GDNF (glial cell derived neurotrophic factor)
Diseases named in the same sentence as GDNF in open-access papers (continued):
Sharing a sentence is not in itself a finding about the gene and the disease.
Parkinson disease (continued). "The essence of our clinical findings is consistent with an earlier randomized, placebo-controlled trial of GDNF in Parkinson’s disease, although the latter used continuous diffusion-dependent intraputamenal delivery resulting in spatially limited putamen delivery." (PMID 30808022, 2019). "We investigated the effects of glial cell line-derived neurotrophic factor (GDNF) in Parkinson’s disease, using intermittent intraputamenal convection-enhanced delivery via a skull-mounted transcutaneous port as a novel administration paradigm to potentially afford putamen-wide therapeutic delivery." (PMID 30808022, 2019). "The study results, while of primary relevance to GDNF and Parkinson’s disease, were considered potentially useful for other applications and indications where direct, targeted drug delivery to brain parenchyma could be beneficial." (PMID 30808022, 2019). "Most studies of GDNF/GFRA1 signaling are related to neurodegenerative (Parkinson’s disease and Alzheimer’s disease) and neuropsychiatric diseases (addiction, bipolar disorder, obsessive compulsive disorder, depression, anxiety, autism, schizophrenia, and attention deficit hyperactivity disorder)." (PMID 29617307, 2018). "Due to its neuroprotective role, GDNF has been tested in the treatment of Parkinson's disease." (PMID 30245717, 2018). "Indeed, the unsuccessful clinical trials investigating the use of GDNF to treat Parkinson’s disease patients used “r-metHuGDNF”, which is a recombinant protein expressed in E. coli." (PMID 28467503, 2017). "There have been multiple clinical trials of GDNF in Parkinson's disease with variable outcomes." (PMID 28911883, 2017). "Indeed, recently a variant of neurturin with reduced affinity for HS was found to diffuse further through brain and to be effective in regenerating dopaminergic nerve fibres a rat model of Parkinson’s disease than GDNF." (PMID 28468283, 2017). "Moreover, the administration of GDNF-expressing macrophages, ameliorated neuroinflammation and neurodegeneration in Parkinson's disease mice." (PMID 28912682, 2017). "Therefore, this study sought to determine the survival and efficacy of primary dopaminergic grafts after intra-striatal delivery in a glial-derived neurotrophic factor (GDNF)-loaded collagen hydrogel in a rat model of Parkinson’s disease." (PMID 29167483, 2017). "The neuroprotective effects of GDNF on various neurons suggested that it could be a good therapeutic candidate for neurodegenerative diseases including Parkinson’s disease and Alzheimer’s disease." (PMID 27657046, 2016). "From a functional point of view, GDNF was originally identified as a potent trophic agent that promotes differentiation and survival of dopaminergic neurons, the main neuronal population affected in Parkinson’s disease." (PMID 27445711, 2016). "In the field of neuroscience, engineered ZF protein transcription factors (ZFP TFs) has been used to improve expression of endogenous glial cell-derived neurotrophic factor (GDNF) in a rat model of Parkinson disease and resulted in improved functional neuroprotection in the brain." (PMID 26528114, 2015). "Whether increasing endogenous GDNF levels is a viable strategy for developing new therapeutic approaches for treating Parkinson’s disease and other diseases is an important question." (PMID 26681446, 2015). "Together, these results imply that measures that promote elevation in endogenous GDNF levels in the striatum may have clinical potential in the treatment of Parkinson’s disease." (PMID 26681446, 2015). "We also found that about two-fold elevation in endogenous GDNF levels protects mice in lactacystin-based model of Parkinson’s disease without side effects associated with ectopic GDNF applications." (PMID 26681446, 2015).
Parkinson disease (continued). "GDNF was first identified as a potent survival factor for midbrain dopaminergic neurons, but was then shown to be a potent neurotrophic factor that had restorative effects in a wide variety of rodent and primate models of Parkinson’s disease." (PMID 24926342, 2014). "Intracerebroventricular GDNF delivered monthly in MPTP-treated monkeys resulted in decreased parkinsonism in a dose responsive manner, attenuated LIDs, and is correlated with increased levels of the DA metabolites 3,4-Dihyroxyphenylacetic acid (DOPAC) and homovanillic acid (HVA)." (PMID 24904259, 2014). "We demonstrate that co-injection of fetal DA neurons with mesencephalic neural stems cells overexpressing GDNF (GDNF-mNSCs) substantially enhances graft survival, NSCs differentiation to DA neurons, and functional improvement in a rat model of Parkinson’s disease." (PMID 24312503, 2013). "In animal model of Parkinson's disease, the delivery of GDNF gene to damaged nigrostriatal system could alleviate the symptoms in rats, which therefore implied a potential clinical use of GDNF for human." (PMID 23878590, 2013). "The fact that GDNF could be regulated is very promising for developing future gene therapies (e.g. for Parkinson's disease) and should be further investigated." (PMID 23029456, 2012). "A number of clinical trials of CED of soluble therapeutic agents have been reported in recent years, including chemotherapies for malignant glioma (topotecan, traberdersan, nimustine) and glial cell line-derived neurotrophic factor (GDNF) for Parkinson's disease." (PMID 22264361, 2012). "On the other hand, neurotrophic factors, in particular GDNF, may be a potential therapeutic approach in the management of Parkinson ́s disease." (PMID 20190960, 2009). "The ability of GDNF-enhancing doses of LY379268to protect nigro-striatal neurons against MPTP toxicity supports the use of mGlu2/3receptor agonists as neuroprotectants in Parkinson's disease." (PMID 19672295, 2009). "Moreover, GDNF stimulates the formation of new axon terminals in dopamine neurons, which has led to an increased interest in the therapeutic potential of GDNF for the management of Parkinson’s disease." (PMID 34803580, 2021). "Prior studies where GDNF was delivered through intraputamen infusion to Parkinson patients showed that that dose as high as 30 ug/day at successive 8-week intervals could be delivered without any systemic toxicity and minimal level of the protein detected in the blood." (PMID 32084217, 2020). "Therefore, the search for new therapies in Parkinson’s disease should now focus on slowing degenerative processes in the GABAergic striatum and restoring fully functional GDNF synthesis—the main chemoattractant for dopaminergic synaptogenesis and neurogenesis and migration of GABA interneurons." (PMID 33171879, 2020). "The collected data allowed to speculate on the GDNF neuroprotective role, thus suggesting its potential in promoting CB cells survival during ageing and its possible role in the use of CB grafts as Parkinson’s disease (PD) therapy to counteract neurological disorders." (PMID 33019660, 2020). "In a rodent model of Parkinson’s disease, viral vector transfer of BDNF and GDNF into nigrostriatal neurons was no more potent than GDNF alone, implying that current striatal changes in GDNF alone may underlie MWM sex differences." (PMID 30356904, 2018). "In conclusion, the encapsulation of dopaminergic neurons in a GDNF-loaded hydrogel dramatically increased their survival and function, providing further evidence of the potential of biomaterials for neural transplantation and brain repair in neurodegenerative diseases such as Parkinson’s disease." (PMID 29167483, 2017). "Glial cell line-derived neurotrophic factor (GDNF) is a potent survival and regeneration-promoting factor for dopaminergic neurons in cell and animal models of Parkinson disease (PD)." (PMID 27607574, 2016).
Parkinson disease (continued). "Similarly, glial-derived neurotrophic factor (GDNF) is a neurotrophin that could be developed as a agent for treatment of Parkinson's disease, stroke, and motor neuron disease." (PMID 25136634, 2014). "For example, in MPTP-induced Parkinsonism, HDAC inhibitors enhanced the expression of GDNF (glial cell-derived neurotrophic factor) and BDNF (brain-derived neurotrophic factor) in astrocytes." (PMID 39057675, 2024). "Both BDNF and GDNF were shown to potentially play a role in the diagnosis of sarcopenia in chronic obstructive pulmonary disease (COPD) and Parkinson’s disease (PD) patients." (PMID 38398421, 2024). "Finally, we sought to create a multimodal index that may predict the early cognitive impairment (prodromal stage) of Parkinson's disease more reliably and precisely by using GDNF as the significant factor and combining it with other illness‐related characteristics and imaging data." (PMID 37718594, 2024). "Additionally, the growing understanding of different neurotrophins such as GDNF highlights the importance of fully grasping the dynamics of neurotrophins in relation to physical activity for the better management of neurodegenerative diseases like Parkinson’s disease." (PMID 38792618, 2024). "The glial cell-derived neurotrophic factor (GDNF), also applied to Parkinson’s disease, has been entrapped in chitosan NLCs, using a combination of solid and liquid lipids." (PMID 34731414, 2022). "This study proves that DA5‐CH can increase the expression of GDNF and BDNF in midbrain tissue, and provide a new direction for the study of the therapeutic mechanism of new GLP‐1/GIP dual agonists for Parkinson's disease." (PMID 34125470, 2021). "Fluoxetine, imipramine, and milnacipran upregulated BDNF and GDNF in the striatum and substantia nigra of rats in the MPTP model of Parkinson’s disease." (PMID 33802323, 2021). "Thereby, glial cell line-derived neurotrophic factor (GDNF), brain-derived neurotrophic factor (BDNF) and nuclear factor E2-related factor 2 (Nrf2) have been studied for Parkinson’s disease treatment." (PMID 33233374, 2020). "For example, glial derived neurotrophic factor (GDNF) was developed as a neurotrophin treatment of a neurodegenerative disease, Parkinson’s disease (PD)." (PMID 33207605, 2020). "Surface-modified lipid nanoparticles were also employed as carriers of glial cell-derived neurotrophic factor (GDNF), a widely studied growth factor used in Parkinson’s disease." (PMID 33291284, 2020). "Another AAV-based neurotrophic factor therapy for human Parkinson’s disease patients has been neurturin (NRTN), a protein in the same family as GDNF." (PMID 28208742, 2017). "Astrocyte-secreted GDNF protected neurons from 6-OHDA-induced cytotoxicity and protected dopamine neurons from apoptosis in an animal model of Parkinson’s disease." (PMID 28489907, 2017). "Intracerebral treatment with glial cell line-derived neurotrophic factor (GDNF) in rodents and monkeys with Parkinson’s symptoms demonstrated an increase of dopamine levels and improvement of motoric behavior." (PMID 27898033, 2016). "Similarly, hNPCs have been modified to release GDNF upon stimulation; cells have been transplanted in the striatum of a rodent model and could survive and effectively express GDNF, paving the way to further studies in Parkinson’s disease animal models." (PMID 25157556, 2014). "Specifically, glial cell-derived neurotrophic factor (GDNF), nerve growth factor (NGF), and brain derived neurotrophic factor (BDNF) have been recognized as therapeutic trophic factors for Parkinson’s, Alzheimer’s and Huntington’s diseases, respectively." (PMID 24463293, 2014). "Previous studies have shown that glial cell line-derived neurotrophic factor (GDNF) family ligands (GFL) are potent survival factors for dopaminergic neurons and motoneurons with therapeutic potential for Parkinson's disease." (PMID 26317008, 2014).
Parkinson disease (continued). "Consequently, while GDNF remains valuable in dopaminergic regeneration, BDNF offers a more feasible and versatile therapeutic option in the current landscape of Parkinson's treatment development." (PMID 41199384, 2025). "It is concluded that BDNF‐PLGA‐NPs, GDNF‐PLGA‐NPs, and TGF‐ß3‐PLGA‐NPs are promising brain drug delivery carriers for NSC inducers, which could be useful in developing strategies for Parkinson's disease management, particularly when targeted with TRF." (PMID 40904189, 2025). "A case report highlighted the adverse effects experienced by a PD patient following GDNF injections, noting a lack of improvement in parkinsonism and a worsening of symptoms, including hallucinations, depression, nausea, and loss of appetite." (PMID 39751928, 2025). "The secondary outcome measures will be the scores of Mini-Mental State Examination (MMSE), Unified Parkinson’s Disease Rating Scale Motor Examination (UPDRSIII) and the level of neurofilament light polypeptide (NfL) and glial cell-derived neurotrophic factor (GDNF)." (PMID 41211292, 2025). "Examples include studies investigating the neuroprotective effects of encapsulated cells delivering glial cell line-derived neurotrophic factor (GDNF) to the brain, l-dopa-secreting cells for Parkinson’s disease, and Nerve Growth Factor (NGF) for Alzheimer’s disease." (PMID 40547419, 2025). "In addition, nobiletin can inhibit the activation of microglia, promote the expression of glial cell line-derived neurotrophic factor (GDNF), and alleviate neurodegeneration in Parkinson’s disease." (PMID 39095693, 2024). "We conclude that endogenous GDNF does not impact the outcome in the LC-induced proteasome inhibition mouse model of Parkinson’s disease." (PMID 36690469, 2023). "In conclusion, given the progress that has been made in the delivery of secreted proteins into the CNS, with GDNF for ALS and Parkinson’s disease as an example, it may be an ideal time to more actively revisit neurotrophic factors for the treatment of ALS." (PMID 37692101, 2023). "Likewise, systemic administration of macrophage-derived exosomes loaded with glial cell-line derived neurotrophic factor (GDNF) reduced neuroinflammation and ameliorated degeneration of dopaminergic neurons in a mouse model of Parkinson’s disease (PD)." (PMID 35299946, 2022). "The independent variables were sex, age, LED, MDS-UPDRS-I, MDS-UPDRS II, MDS-UPDRS III, MDS-UPDRS IV, H-Ystage, NMSS total score, MoCA total score, RLS, PDSS total score, ESS total score, age of onset of motor symptoms, GDNF, RBD, and the motor forms of Parkinson's disease." (PMID 35095724, 2021). "Other long-lasting formulations for the treatment of Parkinson’s disease include PLGA microparticles (delivery of VEGF and GDNF), PLGA-collagen microparticles (delivery of GDNF fused with collagen binding peptide) and poly(butyl cyanoacrylate) nanoparticles (delivery of nerve growth factor, NGF)." (PMID 33096803, 2020). "As Gash’s group has clearly demonstrated for GDNF injections in a non-human primate model of Parkinson’s disease, the amount of improvement motor performance measured by a clinical motor rating scale is directly related to the volume covered." (PMID 32725425, 2020). "This study yielded promising results, but a clinical trial based on the direct infusion of GDNF into the putamen resulted in no significant improvement of Parkinson’s disease symptoms, raising questions about therapeutic efficacy of GDNF." (PMID 33192264, 2020). "Our chemical induction method significantly upregulated various trophic factors, such as BDNF, GDNF, NGF, and NT-3, which have been reported to have therapeutic effects in neurodegenerative diseases, such as Alzheimer’s disease, Parkinson’s disease, and Amyotrophic lateral sclerosis." (PMID 33104750, 2020). "Glial cell line-derived neurotrophic factor (GDNF) is known for its neurorestorative and neuroprotective effects in nonhuman primate models of Parkinson’s disease." (PMID 30829619, 2019).
Parkinson disease (continued). "A recent study, however, found that SNCA (α-synuclein) mRNA is not increased in sporadic Parkinson’s disease, and α-synuclein accumulation does not block GDNF signalling in either Parkinson’s disease or Parkinson’s disease models." (PMID 30808022, 2019). "At this point, therefore, we are not able to identify a priori a particular subgroup of Parkinson’s patients that are either more or less likely to respond to GDNF therapy." (PMID 30808022, 2019). "Glial cell line-derived neurotrophic factor (GDNF) has demonstrated neurorestorative and neuroprotective effects in rodent and nonhuman primate models of Parkinson’s disease." (PMID 29785638, 2018). "Here we compare for the first time the effects of overexpressed α-GDNF and β-GDNF in non-lesioned rat striatum and the partial 6-hydroxydopamine lesion model of Parkinson's disease." (PMID 29973907, 2018). "Following intraventricular, intrastriatal or intranigral delivery, GDNF has reproducibly demonstrated neurorestorative and neuroprotective effects in standard toxin-induced rodent and nonhuman primate models of Parkinson’s disease (PD)." (PMID 29785638, 2018). "Clinical trials of neurotrophic factor therapy for the treatment of Parkinson's disease through direct delivery of recombinant GDNF have failed to display clinical benefit." (PMID 29686604, 2018). "We now report that selective pharmacological activation of mGlu3 receptors enhancesthe production of GDNF in mouse striatum, and that the potent mGlu2/3 receptoragonist, LY379268, is highly protective in the MPTP model of parkinsonism at dosesthat up-regulate GDNF." (PMID 19672295, 2009). "Poly(lactic-co-glycolic acid) nanospheres loaded with VEGF and glial cell line-derived neurotrophic factor (GDNF) effectively decreased the amount of amphetamine-induced rotation behavior andwas involved in neuronal recovery and protection in a partially lesioned Parkinson’s disease rat model." (PMID 35335551, 2022). "Some studies have shown that neurotrophic factors such as glial cell-derived neurotrophic factor (GDNF) and brain-derived neurotrophic factor (BDNF) upregulate tyrosine hydroxylase (TH), improve movement disorders and provide neuroprotection in animal models of Parkinson’s disease." (PMID 35557834, 2022). "Glial cell line-derived neurotrophic factor (GDNF), cerebral dopamine neurotrophic factor (CDNF), and mesencephalic astrocyte-derived neurotrophic factor (MANF) have shown neuroprotective and restorative effects on nigral dopaminergic neurons in various animal models of Parkinson’s disease." (PMID 29349573, 2018). "However, outcome parameters did not significantly differ between GDNF- and placebo-treated patients diagnosed with Parkinson’s disease." (PMID 27898033, 2016). "However, clinical trials in Parkinson’s disease patients after intracerebroventricular administration of recombinant GDNF demonstrated minor or no clinical improvements." (PMID 27286696, 2016). "Glial cell line-derived neurotrophic factor (GDNF), a member of the TGFβ superfamily that signals via cell-surface tyrosine kinase receptors, is considered an essential neuroprotective ligand for midbrain dopaminergic neurons with promising clinical trials in Parkinson's disease." (PMID 24324616, 2013). "Improving overall cell survival might therefore also potentially increase the survival of pre-differentiated cells, but as in Parkinson’s disease additional survival factors (e.g. BDNF, GDNF) might be required to ensure the long-term survival and integration of these neurons." (PMID 22876937, 2012). "However, clinical trials in Parkinson's disease patients delivering GDNF failed to produce significant clinical benefits probably because of either inadequate site of administration or the appearance of side effects." (PMID 21649894, 2011).